ING2 (inhibitor of growth family member 2)
Diseases named in the same sentence as ING2 in open-access papers (continued):
Sharing a sentence is not in itself a finding about the gene and the disease.
squamous cell carcinoma (2 papers, 2019 to 2020). A carcinoma arising from squamous epithelial cells. "A study observed the loss of ING2 expression in 70 out of 120 (58.3%) NSCLC, and was more frequent in adenocarcinoma than in squamous cell carcinoma (68% and 45%, respectively)." (PMID 31640185, 2019). "ING2 loss was correlated with lymph node metastasis status and TNM stage in squamous cell carcinoma, but not in adenocarcinome." (PMID 31640185, 2019). "Moreover, the ING2 gene deep deletion was the most frequent alteration with 17 out of 408 (3.54%) NSCLC and was found to be higher in squamous cell carcinoma than in adenocarcinoma (6.18% and 2.61%, respectively)." (PMID 31640185, 2019). "Interestingly, the analysis of the mSin3A/HDAC complex member alterations in NSCLC via the TCGA database revealed that ING2 was altered in 20 out of 408 (4.9%) NSCLC and was found to be higher in squamous cell carcinoma than in adenocarcinoma (6.7% and 2.6%, respectively)." (PMID 31640185, 2019).
acute kidney injury (1 paper, 2021). Sudden and sustained deterioration of the kidney function characterized by decreased glomerular filtration rate, increased serum creatinine or oliguria. "Consistent with our in vitro data, overexpression of ING2 largely ameliorated the effects of acute kidney injury on the levels MRLP12 protein and its downstream targets." (PMID 34434929, 2021).
ameloblastoma (1 paper, 2019). The most common odontogenic tumor, arising from the epithelial component of the embryonic tooth and usually affecting the molar-ramus region of the mandible or maxilla. "Knockout of some of the ING genes in murine models by various groups has verified their status as tumor suppressors, with ING1 knockout resulting in the formation of large clear-cell B-lymphomas and ING2 knockout increasing the frequency of ameloblastomas, among other phenotypic effects." (PMID 31752342, 2019).
asthma (1 paper, 2022). "Significant DMPs fall within genes involved in the TFG-β related pathways (e.g. BMP2, FLCN, ING2, PMEPA1, PRDM16, TGFB1I1 and TGFBR3), in line with previous studies that reported an association between these genes and the increased asthma risk." (PMID 35619695, 2022).
cutaneous melanoma (1 paper, 2006). A primary melanoma arising from atypical melanocytes in the skin. "In summary, we found that ING2 nuclear expression is reduced in human cutaneous melanomas compared to normal or dysplastic nevi." (PMID 16755297, 2006). "The main purpose of this study is to investigate if the novel tumour suppressor ING2 is aberrantly expressed in human cutaneous melanomas." (PMID 16755297, 2006).
developmental delay (1 paper, 2016). "It is hypothesized that the ING2-induced developmental delay could be due to decreased expression of HDAC1 and concomitant increased expression of p21, and may not be associated with apoptosis because there was no increase in the expression of the pro-apoptotic Bax transcripts." (PMID 25672483, 2016).
diabetic kidney disease (1 paper, 2021). Progressive kidney disorder caused by vascular damage to the glomerular capillaries, in patients with diabetes mellitus. "For example, ING2 enhances EMT in renal proximal tubular cells and is likely to be involved in the development of a main pathological effect in diabetic kidney disease." (PMID 34439818, 2021).
dysplastic nevi (1 paper, 2006). "Our data showed that nuclear ING2 expression was significantly reduced in radial growth phase (RGP), vertical growth phase (VGP), and metastatic melanomas compared with dysplastic nevi (P<0.05)." (PMID 16755297, 2006).
esophageal squamous cell carcinoma (1 paper, 2019). Esophageal squamous cell carcinoma (ESCC) is a type of esophageal carcinoma (EC) that can affect any part of the esophagus, but is usually located in the upper or middle third. "Additionally, deletion of the chromosomic region 4q34–35.2 containing the ING2 gene has also been reported in uterine leiomyosarcoma (3/6), and hypermethylation of the seven CpG sites in multiple intronic regions of the ING2 gene has been shown in patients with esophageal squamous cell carcinoma." (PMID 31640185, 2019).
gastric cancer (1 paper, 2019). A primary or metastatic malignant neoplasm involving the stomach. "In human gastric cancer, the depletion of ING2 caused G0/G1 cell cycle arrest and reduced invasive behavior of cells, suggesting that it acts also as an oncogene for gastric cancers." (PMID 31752342, 2019).
ischemia (1 paper, 2021). A hypoperfusion of the BLOOD through an organ or tissue caused by a PATHOLOGIC CONSTRICTION or obstruction of its BLOOD VESSELS, or an absence of BLOOD CIRCULATION. "Collectively, these data suggested that ING2 participates in ischemia induced TEC injury." (PMID 34434929, 2021). "Furthermore, we demonstrated that ING2 overexpression both in vitro and in vivo could effectively ameliorate ischemia induced TEC mitochondrial injuries and kidney functions, providing ING2 as one potential target for ischemic AKI." (PMID 34434929, 2021).
kidney injury (1 paper, 2021). Trauma to the kidney. "In vivo study suggested that kidney specific ING2 overexpression could effectively ameliorate acute ischemic kidney injury." (PMID 34434929, 2021).
leukemia (1 paper, 2011). A malignant (clonal) hematologic disorder, involving hematopoietic stem cells and characterized by the presence of primitive or atypical myeloid or lymphoid cells in the bone marrow and the blood. "Recent evidence also showed that the PHD finger of ING2 is capable of arresting haematopoietic differentiation and inducing leukemia suggesting that this motif regulates developmentally important genes through interaction with H3K4me3." (PMID 22163049, 2011).
metastatic melanoma (1 paper, 2006). A melanoma that has spread from its primary site to another anatomic site. "Forty-three out of 50 metastatic melanoma cases were available for ING2 staining." (PMID 16755297, 2006). "Our results showed that ING2 nuclear expression did not significantly correlate with both 5-year overall and disease-specific patient survival in primary and metastatic melanomas (P>0.05, log-rank test)." (PMID 16755297, 2006).
sarcoma (1 paper, 2019). A usually aggressive malignant neoplasm of the soft tissue or bone. "Moreover, a study conducted on ING2 knockout mice indicates that ING2 deficiency spontaneously increases soft tissue sarcoma formation." (PMID 31640185, 2019).
Sertoli Cell-Only Syndrome (1 paper, 2010). A type of male infertility in which no germ cells are visible in any of the biopsied SEMINIFEROUS TUBULES (type I) or in which germ cells are present in a minority of tubules (type II). "Considering that germ cells are the major source of ING2 expression in testis, the finding of low ING2 expression in men with Sertoli-cell only syndrome likely reflects the fact that the spermatogenic cell types are absent from the seminiferous tubules." (PMID 21124965, 2010). "Using publicly available gene expression datasets, low expression of ING2 was found in teratozoospermic sperm (>3-fold reduction) and in testes from patients with defective spermatogenesis (>7-fold reduction in Sertoli-cell only Syndrome)." (PMID 21124965, 2010).
teratospermia (1 paper, 2017). "The higher number of common up-regulated genes was found between Etv5 KD and Pou3f1 KD, with 53 genes, Bcl6b KD and Etv5 KD, with 19 genes, Bcl6b KD and Pou3f1 KD, with 14 genes, MArrest and teratospermia, with 12 genes, and MArrest and Ing2 KO, with nine common genes." (PMID 29150651, 2017).
testicular degeneration (1 paper, 2010).
tumor (29 papers, 2006 to 2026). "ING1 and ING2 are localized in the cell nucleus and associated with chromatin modifying enzymes, linking tumor suppression directly to chromatin regulation." (PMID 21767350, 2011). "Future studies on ING2 expression and gene mutation in different cancer types will provide further evidence on the important role of this tumour suppressor in the pathogenesis of human cancers." (PMID 16755297, 2006). "The DNA methylation and expression levels of FAM90A1 and ING2 are associated with tumour regrowth, and may serve as biomarkers for predicting the prognosis of patients with NFPA." (PMID 32015217, 2020). "ING2 (inhibitor of growth family member 2) is a component of a chromatin-regulatory complex that represses gene expression and is implicated in cellular processes that promote tumor suppression." (PMID 23823870, 2013). "Both Inhibitor of Growth factors, ING1 and ING2, belonging to a family of type II tumor suppressors are interacting partners of the AR and mediate cellular senescence." (PMID 41264145, 2025). "Mechanistically, the tumor suppressors ING1b and ING2 mediate AR-induced hTERT repression as corepressors supporting the notion that SAL has tumor suppressive activity." (PMID 41264145, 2025). "ING1 and ING2, for example, modulate cell cycle arrest and apoptosis through androgen receptor signalling, contributing to tumor suppression." (PMID 38813086, 2024). "The identification of ING1 and ING2 tumor suppressors in the AR-mediated transrepression of hTERT provides some first insights into the link between tumor suppressors and the AR (graphical abstract)." (PMID 34439179, 2021). "FAM90A1 and ING2 was found to be independent prognostic factors of tumour regrowth with univariate Cox regression." (PMID 32015217, 2020). "Through prognostic analyses of clinical parameters and six genes, age, FAM90A1 and ING2 was found to be the indenpendent factors of tumour regrowth." (PMID 32015217, 2020). "ING2 expression is usually decreased or lost in many human tumours, but another study found its expression to be upregulated." (PMID 32015217, 2020). "The authors of this study thus propose that ING2 exerts its tumor-suppressive function by directly maintaining DNA integrity." (PMID 31390718, 2019). "Several tumor suppressive functions have been described for ING2 in cancer cell lines, and in accordance with these observations, ING2 expression is lost in many cancer subtypes." (PMID 31640185, 2019). "All of these facts highlight ING2 as a tumor suppressor gene, playing a critical role against tumor development and cancer, notably through the regulation of mSin3A/HDAC-mediated epigenetic functions." (PMID 31640185, 2019). "The degree of similarity between ING1 and ING2 led to ING2‘s classification as a type-II-tumor-suppressor protein." (PMID 31752342, 2019). "The tumour suppressor roles of ING1 and ING2 have been well established whereas candidate tumour suppressor status remains for ING3, ING4, and ING5." (PMID 31905726, 2019). "Although the founding members of the INhibitor of Growth (ING) family of histone mark readers, ING1 and ING2, were defined as tumour suppressors in animal models, the role of other ING proteins in cellular proliferation and cancer progression is unclear." (PMID 29381681, 2018). "The tumor suppressor ING2 is the first confirmed target of miR-8084, and miR-8084 contributes to pro-tumor effect, at least partially, through regulating ING2." (PMID 29471858, 2018). "ING2 is a characterized tumor suppressor which plays an anti-tumor role by affecting cell proliferation, apoptosis and migration." (PMID 29471858, 2018).
tumor (continued). "Consistent with tumor suppressive functions, ING2 regulates several key cellular processes including chromatin structure, cell cycle progression, and cell proliferation." (PMID 23823870, 2013). "An understanding of the gene network controlled by ING2 is critical to unravel the molecular mechanism by which ING2 functions under physiological conditions as a tumor suppressor protein." (PMID 23823870, 2013). "Here we summarize the activity of ING1 and ING2 as tumor suppressors, chromatin factors and in development." (PMID 21767350, 2011). "Taken together, these studies provide evidences that endogenous ING1 and ING2 seem to have diverse functions in tumor suppression and spermatogenesis." (PMID 21767350, 2011). "The role of ING1 and ING2 as tumor suppressor proteins is supported since both factors are involved in cellular senescence, an effective anti-tumor pathway." (PMID 21767350, 2011). "Recent analyses of ING1- and ING2-deficient mice confirm a tumor suppressive role of ING1 and ING2 and also indicate an essential role of ING2 in meiosis." (PMID 21767350, 2011). "ING2 (inhibitor of growth family, member 2) is a member of the plant homeodomain (PHD)-containing ING family of putative tumor suppressors." (PMID 21124965, 2010). "Animal models clearly define ING1 and ING2 as bona fide tumour suppressors." (PMID 33925563, 2021). "Based on these data, we further hypothesized that the ING1 and ING2 tumor suppressors are involved in the AR-mediated transrepression of hTERT." (PMID 34439179, 2021). "Age, expression of FAM90A1 and ING2 are independent prognostic factors of tumour regrowth." (PMID 32015217, 2020). "ING2 is a memeber of the inhibitor of growth family, of which represents as a tumour suppressor." (PMID 32015217, 2020). "As a tumor suppressor gene, several studies have explored ING2 gene status in different types of human tumors, whether at the genomic, transcriptomic or protein level." (PMID 31640185, 2019). "Interestingly, one of the tumor types with the most frequent alteration in ING2 was the lung squamous cell carcinoma, comprising 5.54% of the tumors involved." (PMID 31640185, 2019). "Moreover, the tumor suppressor ING2 is a potential target of miR-8084, and miR-8084 regulatory axes contribute to pro-tumor effect, at least partially through regulating ING2." (PMID 29471858, 2018). "As a candidate tumor suppressive gene, ING2 is frequently decreased expression in human tumors." (PMID 30355852, 2018). "Taken together, these findings support the notion that ING2 plays a key role in DNA damage-induced gene repression, and this activity may be critical for ING2 tumor suppressive functions." (PMID 23823870, 2013). "The finding that ING2 promotes cells differentiation may also explain at a cellular level how ING2 operates in a tumor suppressive manner." (PMID 22808232, 2012). "Although a number of studies indicated that ING2 possesses tumour suppressive functions, such as inducing growth arrest, senescence, apoptosis and enhancing DNA repair, there is limited information on ING2 expression level in human cancers." (PMID 16755297, 2006). "Indeed, experimental studies have demonstrated that ING2 could effectively affect the sensitivity of tumor cells for chemotherapy and radiotherapy and propel tumor cells death." (PMID 34434929, 2021). "Interestingly, loss of ING2 resulted in an elevated incidence of soft-tissue sarcomas, while ING1-deficient mice preferentially developed B-cell lymphomas, supporting the role of ING proteins as tumor suppressors." (PMID 21767350, 2011).
tumor (continued). "These analyses identified several differentially methylated genes linked to invasiveness (e.g., PHYHD1, WNT4, STAT6, CDH1, CDH13), aggressive behaviour (e.g., AIP, PDCD1, LINE-1), and tumour regrowth (e.g., TERT, FAM90A1, ING2)." (PMID 41866138, 2026). "The DNA methylation and expression levels of FAM90A1 (Family with Sequence Similarity 90 Member A1) and ING2 (Inhibitor of Growth Family Member 2) are associated with tumor regrowth in non-functioning PitNETs and may serve as biomarkers for predicting the prognosis in these cases." (PMID 40362297, 2025). "ING1 and ING2, key components in mSIN3a-HDAC complexes, actively repress cell proliferation and tumor growth, also modulating hormonal-epigenetic interplay via androgen receptor signaling." (PMID 38813086, 2024). "The first identified PHD finger binding to PtdIns5P was isolated from the inhibitor of growth protein 2 (ING2), a histone code reader and member of the ING family of tumour suppressors." (PMID 37509085, 2023). "The progression-free analysis found that FAM90A1, ETS2, STAT6, MYT1L, ING2 and KCNK1 are related to tumour regrowth." (PMID 32015217, 2020). "ING2 (inhibitor of growth protein-2) is a member of the ING-gene family and participates in diverse cellular processes involving tumor suppression, DNA repair, cell cycle regulation, and cellular senescence." (PMID 25672483, 2016). "Significant genetic losses were assumed to contain potential tumour-suppressor genes: DPYD (1p21.3); CLDN22, CLDN24, ING2, CASP3, SORBS2 (4q34.2-q35.1); DEFB (8p23.1)." (PMID 26019623, 2015). "Mice lacking ING1 or ING2 develop spontaneous tumours including lymphomas and soft tissue sarcomas, respectively." (PMID 31905726, 2019). "Hence, the data confirm our hypothesis that the tumor suppressors and AR co-repressors ING1 and ING2 functionally mediate the transrepression of androgen-activated AR on hTERT. * p ≤ 0.05." (PMID 34439179, 2021). "Furthermore, ING2 can ablate the expression of the candidate proto-oncogene CIP2A, whereas transcription of matrix metalloproteinase 13 (MMP13) can be activated or repressed by ING2, depending on the cancer type analyzed, thereby regulating tumor invasiveness." (PMID 31752342, 2019). "Taken together, our findings define ING2 and the Sin3A-HDAC1 chromatin remodeling complexes as a novel epigenetic mechanism that promotes muscle differentiation, with important implications for our understanding of ING functions in cell differentiation and tumor suppression." (PMID 22808232, 2012). "Our data that reduced ING2 expression does not significantly correlate with 5-year patient survival is consistent with the findings that ING2 reduction is an early event in the RGP and does not correlate with tumour progression." (PMID 16755297, 2006).